IL6 (interleukin 6)
Diseases named in the same sentence as IL6 in open-access papers (continued):
Sharing a sentence is not in itself a finding about the gene and the disease.
lung adenocarcinoma (continued). "The roles of IL-6 and NK cells in the production and development of GGO provide new insights into the early diagnosis and pathogenesis of lung adenocarcinoma." (PMID 34568032, 2021). "In our previous study, we reported increased levels of IL-4, IL-6, IL-10, and TGF-β detected in the peripheral blood of lung adenocarcinoma patients." (PMID 33167343, 2020). "To identify the definite correlation between HIP-55 and IL-6 in lung adenocarcinoma patients, we conducted an expression and correlation analysis of RNAseq between HIP-55 and IL-6." (PMID 32134471, 2020). "GSEA revealed that low HIP1R mRNA expression was closely associated with allograft rejection, inflammatory responses, IL6-JAK-STAT3, IL2-STAT5, and interferon gamma response pathways in lung adenocarcinoma." (PMID 32403421, 2020). "This early and basic study suggests that the evaluation of inflammatory markers, including IL-6, and quantification of CD8+ T-lymphocytes and their subpopulations can be used to follow-up patients with lung adenocarcinoma." (PMID 33167343, 2020). "The combined classifier of IL-6 and IL-17A was ranked as the best model (AIC=269) to predict survival outcome of stage I lung adenocarcinoma patients." (PMID 28402963, 2017). "qRT/PCR and Western blot results showed that the expression of TNF-α and IL-6 at the mRNA and protein levels were significantly upregulated in AFG1-induced lung adenocarcinoma tissues." (PMID 28801561, 2017). "By integrating two time-course microarray data in human lung adenocarcinoma cells, we specifically have identified some nested gene clusters and found that TGFB1, EGR1, EGR2, EGFR, IL6, JUN, and JUNB all are involved in these clusters." (PMID 28959347, 2017). "We treated A549 with AFG1 and/or TNF-α with IL-6 to investigate to the key contributor of EMT and migration in AFG1-induced lung adenocarcinoma." (PMID 28801561, 2017). "IL‐6 also induces EMT in vitro in immortalized epithelial oral cells, in a JAK2/STAT3/Snail1‐dependent way, in lung adenocarcinoma cells (in a STAT3‐Snail1‐dependent fashion) and in NSCLC cells." (PMID 28599100, 2017). "In this study, we found increased TNF-α and IL-6 expression and macrophages infiltration in AFG1-induced lung adenocarcinoma." (PMID 28801561, 2017). "As expected, STAT1 knockdown partially inhibited IL-17-mediated IL-6, IL-8, and VEGF production in human lung adenocarcinoma cell lines in vitro, suggesting communication between STAT1 signalling and IL-17 in lung adenocarcinoma." (PMID 27819281, 2016). "Our results suggested that IL-6, IL-8 and VEGF expression was positively correlated with IL-17 expression in human lung adenocarcinoma tissues." (PMID 27819281, 2016). "Mutant EGFR genes have been reported to upregulate IL-6 and then activate the gp130/JAK/STAT3 pathway in primary human lung adenocarcinomas." (PMID 27362942, 2016). "In conclusion, we have revealed that IL-17 promotes IL-6, IL-8, and VEGF production in lung adenocarcinoma via STAT1 signalling." (PMID 27819281, 2016). "In our study, the relationship between IL-17, IL-6, IL-8, and VEGF and MVD determined by CD31 staining in human lung adenocarcinoma tissues was explored by qRT-PCR and IHC." (PMID 27819281, 2016). "Collectively, our present results show that enhanced IL-6 expression, via STAT3 phosphorylation, is a mechanism of EMT in lung adenocarcinoma." (PMID 24789104, 2014). "In this study we provide novel evidence that enhanced IL-6 expression, via STAT3 phosphorylation, is a mechanism that can drive EMT and metastasis in lung adenocarcinoma." (PMID 24789104, 2014). "In this study, we showed that IL-6 was involved in EMT and metastasis, via induction of STAT3 phosphorylation in lung adenocarcinoma cells, by in vitro IL-6 stimulation experiments, clinical correlation analysis and xenograft experiments." (PMID 24789104, 2014).
lung adenocarcinoma (continued). "To investigate this point, we first examined the effect of IL-6 on STAT3 tyrosine phosphorylation in A549 and HCC827 lung adenocarcinoma cells." (PMID 24789104, 2014). "Metformin can inhibit IL-6 induced EMT by blocking STAT3 phosphorylation, suggesting a potential clinical use of metformin in the treatment of lung adenocarcinoma." (PMID 24789104, 2014). "We previously demonstrated that autocrine IL-6-activated Stat3 contributes to tumor metastasis and upregulation of VEGF, resulting in the generation of MPE in lung adenocarcinoma." (PMID 24086497, 2013). "Together, we found that the expression of TF regulated by IL-6/JAK2/Stat3 signaling promotes tumor metastasis and MPE formation in an animal model of lung adenocarcinoma." (PMID 24086497, 2013). "The five largest node targets identified were protein kinase 1 (AKT1), STAT3, JUN, interleukin-6 (IL-6), and mitogen-activated protein kinase 3 (MAPK3), which may be important targets for the treatment of lung adenocarcinoma with QSFZYL." (PMID 40642092, 2025). "In the tumor microenvironment (TME), a complex network of factors could be involved in CD155 overexpression; therefore, we evaluated whether the correlation between IL-6 and CD155 is preserved in lung adenocarcinoma tissues." (PMID 39596207, 2024). "IL-6 and SOCS1 are critical regulators of CD155 expression in lung adenocarcinoma." (PMID 39596207, 2024). "Recently, researchers again confirmed that IL-6 can effectively construct the inflammatory microenvironment of lung adenocarcinoma liver metastasis in vitro, increasing the proliferation, metastasis, and EMT of lung adenocarcinoma cells." (PMID 36578520, 2022). "Although the changes of IL-6 and NK cells in lung adenocarcinoma have caught global attention, we have little appreciation for how IL-6 and NK cells in the lung GGO affect the progression of early lung adenocarcinoma." (PMID 34568032, 2021). "This study suggests that in addition to the known inflammatory markers, IL-6, CD8+ T-lymphocytes and their effector and naïve subpopulations could be useful as predictive markers in lung adenocarcinoma." (PMID 33167343, 2020). "Correlation analysis showed that there was a strong negative correlation between HIP-55 and IL-6 in lung adenocarcinoma patients." (PMID 32134471, 2020). "This early study suggests that the quantification of inflammatory markers, including IL-6, and CD8+ T-lymphocytes and their subpopulations could be used during follow-up of clinical response in patients with lung adenocarcinoma." (PMID 33167343, 2020). "This indicates that the co-expression of TIMP-1 and IL-6 has a negative impact on the survival of lung adenocarcinoma patients." (PMID 31443242, 2019). "Given that IL6 over expression is strongly correlated with malignant behavior in NSCLC, especially in lung adenocarcinoma, the expression of ERβ and IL6 in a normal bronchial epithelial cell line (HBE) and lung adenocarcinoma cell lines A549 and H1793 was evaluated by western blot." (PMID 29970138, 2018). "Importantly, ERβ/IL6 expression was identified as an independent prognostic factor for NSCLC, with higher IL6 expression indicating a shorter overall survival in lung adenocarcinoma." (PMID 29970138, 2018). "Overall survival was shorter in patients exhibiting high expression of IL6 than in those showing low expression in the lung adenocarcinoma group (P < 0.001, log-rank test), but not in the lung squamous cell carcinoma group (P = 0.3175, log-rank test)." (PMID 29970138, 2018). "Similarly, Stk24 silencing inhibited the IL-17-induced expression of IL-6, CXCL2, and CCL20 in human lung adenocarcinoma cells A549." (PMID 29760709, 2018). "The expression of TNF-α, IL-6, and macrophage marker CD68, as well as E-cadherin, vimentin, Twist, matrix metalloproteinase (MMP)-2, MMP-9, and SOD-2 were examined in AFG1-induced lung adenocarcinoma." (PMID 28801561, 2017).
lung adenocarcinoma (continued). "Taken together, the results suggest that TNF-α working together with IL-6 could promote EMT and migration in A549 cells, and TNF-α is the key contributor of EMT and migration in AFG1-induced lung adenocarcinoma." (PMID 28801561, 2017). "In conclusion, IL-17 may promote the production of the angiogenic inducers IL-6, IL-8 and VEGF via STAT1 signalling in lung adenocarcinoma." (PMID 27819281, 2016). "Moreover, it was also reported that metformin was able to depress IL-6-induced EMT possibly by blocking STAT3 phosphorylation, thereby inhibiting the growth and metastasis of lung adenocarcinoma." (PMID 27105507, 2016). "Importantly, positive correlations were also detected between IL-17 expression and IL-6, IL-8 and VEGF expression in human lung adenocarcinoma tissues." (PMID 27819281, 2016). "Taken together, these data indicate that IL-17 may promote IL-6, IL-8 and VEGF production in human lung adenocarcinoma in vitro." (PMID 27819281, 2016). "We discovered that IL-6, via STAT3 phosphorylation, could promote lung adenocarcinoma cell invasion via EMT in vitro." (PMID 24789104, 2014). "In an elegant series of experiments Chen and colleagues showed that AhR could induce IL-6 expression and NF-κB activity in BEAS-2B cells and H1355 human lung adenocarcinoma cells." (PMID 25201625, 2014). "Collectively, these results not only suggest that the IL-6/IL-6R/STAT3 may be used as molecular targets for the inhibition of IL-6-induced EMT, but also provide experimental evidence for the potential use of metformin in the treatment of lung adenocarcinoma." (PMID 24789104, 2014). "The results showed that metformin treatment could significantly reduce IL-6-induced STAT3 phosphorylation in A549, HCC827 and HCC827-pSB388 lung adenocarcinoma cells in a dose-dependent manner." (PMID 24789104, 2014). "We found that metformin could inhibit IL-6 induced EMT possibly by blocking STAT3 phosphorylation, suggesting a potential clinical use of metformin in treatment of lung adenocarcinoma." (PMID 24789104, 2014). "We found that IL-6 transfection significantly promoted the growth of HCC827 tumors, consistent with the previous findings of a pro-tumor activity of IL-6 in lung adenocarcinoma." (PMID 24789104, 2014). "To determine whether IL-6 is involved in EMT, we first examined the effect of IL-6 on the morphology of lung adenocarcinoma cells." (PMID 24789104, 2014). "Our results indicate IL-6/JAK2/Stat3 pathway also regulates TF expression, which is an important regulator for tumor formation, lung metastasis, and malignant effusion generation in lung adenocarcinoma bearing activated Stat3." (PMID 24086497, 2013). "However, the role of Jak-Stat family signalling, such as STAT1 signalling, in the IL-17-mediated regulation of IL-6, IL-8 and VEGF in lung adenocarcinoma remains unknown." (PMID 27819281, 2016). "Furthermore, MVD was also positively correlated with the IL-17, IL-6, IL-8, and VEGF mRNA level, suggesting that IL-17, IL-6, IL-8, and VEGF may be involved in angiogenesis in human lung adenocarcinoma." (PMID 27819281, 2016). "Network analysis in non-smoking female lung adenocarcinoma patients described IL-6 as one of the pathology’s central nodes, and these findings agree with our results, which provide evidence of the critical role of IL-6 in tumor progression in female lung adenocarcinoma patients." (PMID 33526761, 2021). "Since IL-6, through JAK/STAT3 signaling, might be involved in EMT in lung adenocarcinoma, and metformin can inhibit EMT and STAT3 phosphorylation in other cancer types, we hypothesized that metformin might be able to inhibit IL-6-induced EMT and growth and metastasis in lung adenocarcinoma." (PMID 24789104, 2014). "Interestingly, the lung adenocarcinoma cell lines that displayed low expression of the negative regulator Suppressor of Cytokine Signaling 1 (SOCS1) showed increased CD155 expression after IL-6 stimulation, in contrast to those that showed high SOCS1 expression." (PMID 39596207, 2024).
lung adenocarcinoma (continued). "In specimens from lung adenocarcinoma patients, correlation analysis of RNAseq revealed that there was a negative correlation between HIP-55 and IL-6." (PMID 32134471, 2020). "The combined prognostic role of IL-6, CRP plus IL-17A in stage I lung adenocarcinoma has not been reported previously." (PMID 28402963, 2017).
Neonatal sepsis (106 papers, 2007 to 2026). Systemic inflammatory response to infection in newborn babies. "The results regarding the association between IL6-174G/C polymorphism and the risk for early-onset neonatal sepsis are controversial." (PMID 41598258, 2026). "When considered alongside conventional markers such as CRP and PCT, IL-6 appears to add additional diagnostic value, supporting the rationale for a combined biomarker approach in early neonatal sepsis evaluation." (PMID 41302151, 2025). "Funisitis was identified in 25% of cases and was significantly associated with elevated cord blood IL-6 levels, lower gestational age, increased rates of microbial invasion of the amniotic cavity, and congenital neonatal sepsis." (PMID 41010644, 2025). "Meeting these gaps, we conducted this meta-analysis to pool the available evidence about the diagnostic performance of IL-6 in neonatal sepsis, particularly in LONS." (PMID 40892314, 2025). "Similar uncertainties exist regarding the association of neonatal sepsis risk with the CC genotype of the IL-6-174G/C polymorphism and the TT, TT+AA genotype of the IL-8-rs4073 polymorphism." (PMID 38848433, 2024). "Previous studies have demonstrated that cytokines such as IL-6, IL-8, IL-10, and IL-27 were biomarkers of neonatal sepsis and their diagnostic properties have been investigated." (PMID 38027268, 2023). "The diagnostic validity of IL-6, IL-8, IL-10 and IL-27 for neonatal sepsis were investigated in several cross-sectional studies and meta-analyses." (PMID 38027268, 2023). "According to systematic reviews, PCT and IL-6 are potential biomarkers for neonatal sepsis, but their reported diagnostic utilities in neonatal sepsis vary between studies and remain to be vaguely established." (PMID 33211747, 2020). "The objective of this study is to investigate the early diagnostic value of IL-6 for neonatal sepsis with PROM." (PMID 30461611, 2018). "IL-6 is therefore a sensitive and specific diagnostic marker for the early diagnosis of neonatal sepsis with PROM." (PMID 30461611, 2018). "The diagnostic accuracy of IL-6 in early onset neonatal sepsis was 16.6 times higher than that in early/late-onset neonatal sepsis (RDOR = 16.6, 95% CI: 1.31–209.61; P = .0351)." (PMID 30461611, 2018). "Previous studies demonstrated procalcitonin, TNF-α, and IL-6 to be the most sensitive and specific diagnostic markers of neonatal sepsis." (PMID 28367457, 2017). "Interleukin-1 has been described as a marker of neonatal sepsis, although its diagnostic efficacy is lower than that of IL-6 and TNF-α." (PMID 25614712, 2014). "Six studies addressing the association between the SNP IL-6-174 and neonatal sepsis were identified." (PMID 24310803, 2013). "Two of them showed that there was a small risk associated with the SNP IL-6-174 C allele and neonatal sepsis." (PMID 24310803, 2013). "Another study, with a large cohort that included 1206 VLBW preterm infants, mostly Caucasian, was equally unable to show any association between the SNP IL-6-174 and neonatal sepsis." (PMID 24310803, 2013). "The first study40included 157 neonates (< 32 weeks) predominantly composed of Caucasians (92%) and showed that there was a risk of neonatal sepsis associated with the SNP IL-6-174 GG (odds ratio, OR = 2.7; P = 0.01; in comparison with GA/AA)." (PMID 24310803, 2013). "The results showed that the OR value of the IL-6-174G/C polymorphism merged in the recessive gene model was statistically significant (P = 0.000), indicating a significant increase in the risk of neonatal sepsis with the CC genotype (OR = 1.591, 95% CI: 1.154–2.194)." (PMID 38848433, 2024). "Studies suggest that assessing presepsin and CRP, PCT or IL-6 together may improve diagnostic procedures and patient outcomes particularly in neonatal sepsis." (PMID 38921759, 2024).
Neonatal sepsis (continued). "Nevertheless, it should be taken into consideration that the elevation of IL-6, for example, has been described to be associated with neonatal sepsis, which could lead to a misleading diagnosis." (PMID 37084165, 2023). "Elevated IL-6 concentrations showed associations with all types of neonatal sepsis." (PMID 36233706, 2022). "The main objective for this review was to assess the diagnostic potential of IL-6, alone and in combination, for diagnosis of early neonatal sepsis (EONS) in term and preterm infants, in cord and peripheral blood, and in dependence of timing of sample collection." (PMID 35402358, 2022). "Interpretation of IL-6 levels for diagnosis of neonatal sepsis therefore might be hampered by underlying illnesses and their severity." (PMID 35345614, 2022). "However, in our study, we first conducted a systematic review and meta-analysis to investigate the early diagnostic value of IL-6 as a potential biomarker for neonatal sepsis with PROM." (PMID 30461611, 2018). "Therefore, we conducted a meta-analysis to systematically assess all published studies on the diagnostic performance of IL-6 for detecting neonatal sepsis with PROM." (PMID 30461611, 2018). "This meta-analysis shows that IL-6 might be a sensitive and specific diagnostic marker for the early diagnosis of neonatal sepsis with PROM." (PMID 30461611, 2018). "One of the most studied pro-inflammatory cytokines is IL-6, which has pleiotropic effects involving the activation of the acute phase of the immune response; it has also been used as a hallmark of the fetal inflammatory response syndrome and early neonatal sepsis." (PMID 32033312, 2020). "(i) It is an innovative study that directs the spotlight onto the effect of the presence of TLR2, TLR4, IL6, and IL10 polymorphisms in the context of early neonatal sepsis in preterm neonates." (PMID 41598258, 2026). "Elevated serum levels of several pro-inflammatory cytokines—such as IL-6, IL-8, IL-10, IL-1β, TNF-α, and MCP-1—have been associated with neonatal sepsis." (PMID 40948499, 2025). "The findings from our study contribute to the growing body of evidence on the role of IL-6 in diagnosing neonatal sepsis and NEC, underscoring the importance of early and accurate diagnosis in improving outcomes for this vulnerable population." (PMID 39958363, 2025). "Interleukin-6 (IL-6), a proinflammatory cytokine, is a proven biomarker for the early detection of neonatal sepsis." (PMID 39958363, 2025). "IL-6 is a biomarker with high sensitivity and specificity for late-onset neonatal sepsis, with good rule-in and rule-out potential." (PMID 40892314, 2025). "During neonatal sepsis in preterm newborns, serum cytokine levels of IL-6 and TNF-α can reach up to 10,000 pg/mL and 1,000 pg/mL respectively." (PMID 38562936, 2024). "Further, cytokines, e.g., interleukin-6 (IL-6) has been suggested as an indicator of neonatal sepsis." (PMID 38517573, 2024). "The pro-inflammatory molecules IL-6, IL-8, and TNF-α, which are increased in PHH, have also been associated with neonatal sepsis with PROM." (PMID 38383424, 2024). "Interleukin-6 (IL-6) is involved in the pathological process of many clinical diseases, and is related to the occurrence of bacterial infection, neonatal sepsis and other inflammatory diseases." (PMID 39139176, 2024). "These major differences in the production of TNF-α and IL-6 between individuals are also observed in serum samples collected during neonatal sepsis." (PMID 38562936, 2024). "The sensitivity of YKL-40 for detecting neonatal sepsis is also similar to that of the cytokines IL-6 and IL-8 (79–83% and 78%, respectively)." (PMID 37238320, 2023). "Interleukins including IL-6, IL-8, IL-10, and IL-27 demonstrated favorable performance in the detection of neonatal sepsis." (PMID 38027268, 2023).